SMURF1 (SMAD specific E3 ubiquitin protein ligase 1)
Description:
E3 ubiquitin-protein ligase that acts as a negative regulator of BMP signaling pathway. Mediates ubiquitination and degradation of SMAD1 and SMAD5, 2 receptor-regulated SMADs specific for the BMP pathway. Promotes ubiquitination and subsequent proteasomal degradation of TRAF family members and RHOA. Promotes ubiquitination and subsequent proteasomal degradation of MAVS. Acts as a positive regulator of smoothened signaling pathway by mediating ubiquitination of PTCH1, leading to endocytosis and lysosomal degradation of PTCH1 (By similarity). Acts as an antagonist of TGF-beta signaling by ubiquitinating TGFBR1 and targeting it for degradation. Plays a role in dendrite formation by melanocytes.
Synonyms: KIAA1625
Tractability: Small molecule: a high-quality ligand is known. Antibody: UniProt places it where antibodies can reach, with high confidence; its Gene Ontology location is reachable by antibodies, with high confidence. PROTAC: UniProt records ubiquitination sites on it; ubiquitination databases record sites on it; a small molecule that binds it is known.
Target class: Enzyme; Transferase
Gene: Protein-coding gene on chromosome 7 (99,027,435 to 99,144,164, reverse strand). Ensembl gene ENSG00000198742.
Subcellular location: Cytoplasm; Cell membrane
Subcellular location (Human Protein Atlas): Vesicles; Nucleoplasm
Pathways (Reactome):
Signal Transduction: Asymmetric localization of PCP proteins; Downregulation of TGF-beta receptor signaling; Hedgehog 'on' state; Signaling by BMP; TGF-beta receptor signaling in EMT (epithelial to mesenchymal transition)
Gene expression (Transcription): Regulation of RUNX2 expression and activity; Regulation of RUNX3 expression and activity
Immune System: Antigen processing: Ubiquitination & Proteasome degradation
Gene Ontology:
Molecular function: activin receptor binding; I-SMAD binding; protein binding; R-SMAD binding; transforming growth factor beta receptor binding; ubiquitin protein ligase activity; ubiquitin-protein transferase activity; phospholipid binding; SMAD binding
Biological process: BMP signaling pathway; cell differentiation; engulfment of target by autophagosome; negative regulation of activin receptor signaling pathway; negative regulation of BMP signaling pathway; negative regulation of MyD88-dependent toll-like receptor signaling pathway; negative regulation of osteoblast differentiation; negative regulation of transforming growth factor beta receptor signaling pathway; positive regulation of dendrite extension; positive regulation of ubiquitin-dependent protein catabolic process; proteasome-mediated ubiquitin-dependent protein catabolic process; protein export from nucleus; protein localization to plasma membrane; protein polyubiquitination; protein targeting to vacuole involved in autophagy; receptor catabolic process; substrate localization to autophagosome; ubiquitin-dependent protein catabolic process; ectoderm development; lysosomal protein catabolic process; positive regulation of smoothened signaling pathway; Wnt signaling pathway, planar cell polarity pathway; positive regulation of axon extension; protein ubiquitination
Cellular component: cytoplasm; extracellular exosome; mitochondrion; nucleus; plasma membrane; cytosol; nucleoplasm; axon; lysosome; neuronal cell body
Genetic constraint (gnomAD): Loss-of-function variants: 43 observed, 91.76 expected, observed/expected ratio (o/e) 0.47, 90% interval 0.37 to 0.6. The upper end of that interval is the gene's LOEUF score, 0.6, which puts it in group 2 of 6, group 1 being the genes least tolerant of losing a copy. Missense variants: 677 observed, 925.64 expected, observed/expected ratio (o/e) 0.73, 90% interval 0.69 to 0.78. Synonymous variants: 392 observed, 371.68 expected, observed/expected ratio (o/e) 1.05, 90% interval 0.97 to 1.15.
Homologues: Orthologues: chimpanzee SMURF1 (100% identical), macaque SMURF1 (99% identical), dog SMURF1 (99% identical), guinea pig SMURF1 (99% identical), rat Smurf1 (99% identical), mouse Smurf1 (99% identical), pig SMURF1 (98% identical), rabbit SMURF1 (95% identical), zebrafish smurf1 (91% identical), tropical clawed frog smurf1 (88% identical). Paralogues in human: SMURF2 (78% identical), ITCH (40% identical), WWP1 (40% identical), WWP2 (39% identical), HUWE1 (38% identical), HECW1 (37% identical), NEDD4L (36% identical), HECW2 (35% identical), NEDD4 (34% identical), HACE1 (29% identical), UBE3C (22% identical), UBE3B (22% identical), and 12 more.
Diseases named in the same sentence as SMURF1 in open-access papers:
SMURF1 is named in the same sentence as 98 diseases in open-access papers, as found by Europe PMC text mining. Sharing a sentence is not in itself a finding about the gene and the disease. The quoted sentences say what the papers report.
breast carcinoma (26 papers, 2013 to 2026). "Here we report that the HECT family ubiquitin ligase SMURF1 associates with and stabilizes ER alpha protein in the cytoplasm in breast cancer cells, which subsequently leads to increased estrogen signaling activity and cell proliferation." (PMID 29433542, 2018). "For example, our previous studies showed that RNF181 and SMURF1 could associate with ERα and promote breast cancer proliferation." (PMID 38017133, 2024). "SMURF1 is also implicated in bone metastasis in breast cancer models by increasing TGFβ signaling." (PMID 33418880, 2021). "In breast cancer, overexpressed Smurf1 resulted in disrupted F‐actin cytoskeletal organization, reduced cell adhesion, increased cell migration and invasion, and promoted tumour metastasis." (PMID 36579844, 2023). "Numerous researches suggest a pivotal role of Smurf1 in cancer progression, including breast cancer, colon cancer, and pancreatic cancer." (PMID 35654587, 2022). "Further opposition comes from other investigation showing that USF2 inhibits the transcriptional activity of Smurf1 and Smurf2 to promote breast cancer cells proliferation, migration and invasion." (PMID 36319631, 2022). "Given that overexpression of JWA (by transfection of Flag-JWA) suppresses migration and invasion in TNBC cells in vitro, and JAC1 inhibits HER2 positive breast cancer cells proliferation by JWA-triggered E3 ubiquitin ligase SMURF1." (PMID 35383155, 2022). "Increasing evidence has shown that SMURF1 is a potential tumor-promoting factor in various cancers, including pancreatic cancer, breast cancer, colorectal cancer, clear cell renal cell carcinoma, head and neck squamous cell carcinoma, and gastric cancer." (PMID 33961622, 2021). "SMURF2 acts as a ubiquitinating enzyme for SMURF1 and hence promotes degradation of its sister protein in the early stages of breast cancer." (PMID 33418880, 2021). "Taken together, we have revealed that JAC1 inhibited the proliferation of breast cancer cells by activating SMURF1." (PMID 33875644, 2021). "In this way, Smurf2 induces ubiquitin-dependent degradation of Smurf1 and prevents migration of breast cancer cells." (PMID 33114139, 2020). "Then, Smurf1 disrupted the stability of growth-inhibitory protein RhoA by ubiquitinating and degrading RhoA, thereby promoting breast cancer cell mobility and plasticity." (PMID 33718111, 2020). "Accordingly, knockdown of Smurf2 enhances Smurf1 levels, increasing breast cancer cell migration and metastasis in vivo." (PMID 33114139, 2020). "In conclusion, our study reveals a novel positive feedback between SMURF1 and ER alpha signaling in supporting breast cancer growth." (PMID 29433542, 2018). "In order to confirm the role of SMURF1 in ER alpha signaling, we utilized one selective SMURF1 inhibitor –A01 to treat breast cancer cell lines." (PMID 29433542, 2018). "The authors also demonstrated that Smurf1 stabilizes estrogen receptor alpha (ERα) in breast cancer cells, leading to increased estrogen signaling and enhanced cell proliferation." (PMID 30116722, 2018). "Since ER alpha signaling is pre-dominant in ER alpha positive breast cancer cells, we further analyzed ER alpha target genes expression change by SMURF1 depletion." (PMID 29433542, 2018). "Although ER alpha has been well documented to have a critical in cancer progression in breast cancer, SMURF1 emerges to be a new component of ER alpha signaling in breast cancer." (PMID 29433542, 2018). "This pro-proliferative and pro-oncogenic effect of SMURF1 in breast cancer was found to be the case with SMURF2 too." (PMID 30619734, 2018). "In order to investigate the role of SMURF1 in breast cancer cells, SMURF1 was depleted in MCF-7 and T47D cells." (PMID 29433542, 2018). "Our study reveals a novel positive feedback between SMURF1 and ER alpha signaling in supporting breast cancer growth." (PMID 29433542, 2018).
breast carcinoma (continued). "To approach the function of SMURF1 in breast cancer cells in an unbiased way, we depleted SMURF1 in MCF-7 breast cancer cells for the whole genomic expression analysis." (PMID 29433542, 2018). "Here, we identify the oncogenic role of SMURF1 in supporting estrogen signaling and breast cancer progression." (PMID 29433542, 2018). "The findings suggest that the downregulation of SMURF1 in breast cancer may contribute to tumor progression by enhancing Wnt/β-catenin signaling activity." (PMID 41752056, 2026). "SMURF1 promotes the migration of breast cancer cells through ubiquitination and RhoA degradation." (PMID 40342823, 2025). "However, it dramatically attenuated the lung metastasis of the breast cancer cells, confirming that Smurf1 phosphorylation is required for EMT and tumor metastasis." (PMID 35654587, 2022). "Then we generated Smurf1-WT or Smurf1-T223A expressing breast cancer cells by reintroducing Smurf1-WT or Smurf1-T223A into Smurf1 knockdown cells, and injected the cells into the mammary fat pad of female BALB/c mice to examine the primary tumor growth and lung metastasis." (PMID 35654587, 2022). "Smurf1 and Smurf2 exert opposite roles in modulating breast cancer progression." (PMID 33718111, 2020). "By analyzing the public available microarray data in breast cancer, we observed SMURF1 mRNA level could be induce by estradiol treatment." (PMID 29433542, 2018). "On this basis, SMURF1 inhibition, which breaks the positive feedback loop, could be a strategy to inhibit cell proliferation in ER alpha positive breast cancers." (PMID 29433542, 2018). "We predicted that 6 genes including ANXA1 would be regulated by miR196a using 4 prediction softwares (TargetScan, MiRanda, Diana MicroT and PicTar), and confirmed the reduction of these genes (ANXA1, HOXA7, HOXB7, ING5, CDC73 and SMURF1) by miR-196a in breast cancer cells using qPCR analysis." (PMID 27105503, 2016). "Importantly, depletion of USP9X in MDAMB231 metastatic breast cancer cells, which have elevated SMURF1 expression, inhibits SMURF1-dependent breast cancer cell motility." (PMID 25606592, 2014). "SMURF1 also shows tumor-promotor activity in breast cancer cells where the ubiquitination function of SMURF2 can promote SMURF1 degradation and, consequently, may rescue important tumor suppressive substrates of SMURF1 to prevent malignant migration of tumor cells." (PMID 36918822, 2023). "Therefore, we could conclude that Smurf1 facilitates breast cancer cell migration in a RhoA-dependent manner." (PMID 33718111, 2020). "Thus targeting SMURF1 could be a promising strategy or drug target for several kinds of human carcinomas, including ER alpha positive breast cancer." (PMID 29433542, 2018). "Targeting SMURF1 could be one promising strategy for ER alpha positive breast cancer treatment." (PMID 29433542, 2018). "This study aimed to evaluate the mRNA and protein levels of SMURF1 and SMURF2 in breast cancer and to elucidate their potential biological roles through in silico analyses." (PMID 41752056, 2026). "Our previous research demonstrated that SMURF1, TRIM56 and RNF181 can interact with ERα and enhance breast cancer growth." (PMID 39215346, 2024). "Blockade of phosphorylation of Smurf1 inhibits TGFβ-induced EMT, and accordingly, dramatically blocks lung metastasis of murine breast cancer in mice." (PMID 35654587, 2022). "USF2 has been reported to downregulate Smurf1 and Smurf2, thereby regulating the TGF-β pathway in breast cancer." (PMID 35255935, 2022). "Its mechanism of action in breast cancer was through the cascade regulations of the two E3 ubiquitin ligases (NEDD4 and SMURF1), which eventually enhanced the ubiquitination modification of HER2 at K716." (PMID 33875644, 2021). "Although Smurf1 inhibits TGF-β signaling through ubiquitination and degradation of p-Smad2 in breast cancer cells, it facilitates tumor development in other ways." (PMID 33718111, 2020).
breast carcinoma (continued). "Thus, SMURF1 and SMURF2 inducers can be considered as effective treatments for HCC and breast cancer, respectively." (PMID 36918822, 2023). "In another study, in breast cancer cells ubiquitination of Smurf1 could be reversed by the deubiquitinating enzyme USP9X through Smurf1 WW domain binding, which improved Smurf1’s stability." (PMID 33718111, 2020). "In breast cancer cells, the mechanism of Smurf1 ubiquitination mediated by Smurf2, as well as Smurf1-induced mechanisms independent of TGF-β signaling, need to be further studied." (PMID 33718111, 2020). "In another study, induction of Smurf1 expression either by EGF or by overexpression of MEK1, as well as Smurf1 overexpression, significantly increased migration and invasion of breast carcinoma MDA-MB-231 cells, whereas knockdown of Smurf1 suppressed the phenotype." (PMID 30116722, 2018). "In addition, SMURF1 expression is elevated and required for MDA-MB-231 breast cancer cells motility." (PMID 30619734, 2018). "Besides, a combination treatment by NEDD4-1 and WWP1 inducers for melanoma cancer, NEDD4-1 and ITCH inhibitors for prostate cancer, NEDD4-1 and SMURF1 for the HCC, as well as SMURF2 inducers and ITCH inhibitors for the breast cancer can be considered as the effective therapeutic approaches." (PMID 36918822, 2023). "Although a previous research has reported that SMURF1 can ubiquitinate HER2 when triggered by a compound JAC1, SMURF1 targeted by TRAF4 has not been validated, whereas SMURF2 has been shown to be targeted by TRAF4 for promoting TGF-beta signaling and facilitating breast cancer metastasis." (PMID 35864174, 2022). "In the present study, we identified for the first time that JAC1, the JWA gene agonist, could inhibit the proliferation of breast cancer cells by enhancing the ubiquitin modification of HER2 at the K716 site and accelerating its degradation through SMURF1 E3 ligase." (PMID 33875644, 2021). "We postulate that the negative effect of Smurf1 on TGF-β signaling is completely offset by the downregulation (in protein levels and ubiquitin ligase activity) of Smurf2, with the final result being enhanced TGF-β signaling that promotes breast cancer progression." (PMID 33718111, 2020).
colorectal cancer (13 papers, 2014 to 2026). A primary or metastatic malignant neoplasm that affects the colon or rectum. "Therefore, upregulation of Smurf1 is associated with poor prognosis in colorectal cancer; however, the detailed mechanisms need to be further investigated." (PMID 33718111, 2020). "For example, IRAK2 mediates the phosphorylation of Smurf1, which triggers ER stress-mediated apoptosis in colorectal cancer cells." (PMID 37108068, 2023). "The ubiquitin ligase Smurf1 can affect the progression and the poor prognosis of colorectal cancer through the activation of canonical neddylation and its specific neddylation at the C426 site." (PMID 37777749, 2023). "In regard to the activation of Smurf1 via neddylation, increased expression of Smurf1 and Nedd8 in colorectal cancer correlates with robust cancer progression and poor prognosis." (PMID 27036023, 2016). "In human colorectal cancer, elevated expression of SMURF1 has been shown to correlate with cancer progression and prognosis." (PMID 25471937, 2014). "In addition, RRP9, as a substrate for Smurf1, promotes the processing of Pre-rRNA and the occurrence of colorectal cancer by interacting with Smurf1 to mediate neddylation at K221." (PMID 37777749, 2023). "Furthermore, heightened RRP9 and Smurf1 expression correlates with the progression of human colorectal cancer." (PMID 37988222, 2023). "It has been shown that FOSL1 can promote the development and invasion of colorectal cancer through the Smurf1-mediated FBXL2/Wnt/β-catenin axis and the migration, invasion, and proliferation of breast, head, and neck squamous cell carcinoma, pancreatic cancer, bladder cancer, and prostate cancer." (PMID 36061185, 2022). "Smurf1 has also been shown to be activated by neddylation in colorectal cancer cells." (PMID 33718111, 2020). "Meanwhile, in colorectal cancer cells, autoubiquitination and degradation of Smurf1, which is induced by ER stress stimulated IRAK2-mediated phosphorylation also at Thr145, Thr161, and Thr682, results in an altered cascade of ER effectors to inhibit cell growth and promote apoptosis." (PMID 33718111, 2020). "In colorectal cancer cells, phosphorylation by Akt1/2 on Smurf1 Thr145 augments Smurf1 protein stability to control DAB2IP abundance, which contributes to increased ubiquitination and degradation of tumor suppressor DAB2IP, dampening DAB2IP’s inhibitory effect on tumor cells." (PMID 33718111, 2020). "In this regard, the capability of Smurf1 activated by neddylation to facilitate physiological processes of colorectal cancer cells maybe also in a manner independent of TGF-β signaling." (PMID 33718111, 2020).